GHET1 (gastric carcinoma proliferation enhancing transcript 1)
Diseases named in the same sentence as GHET1 in open-access papers (continued):
Sharing a sentence is not in itself a finding about the gene and the disease.
cancer (15 papers, 2016 to 2021). A tumor composed of atypical neoplastic, often pleomorphic cells that invade other tissues. "The odds ratios (ORs) and 95% CIs were calculated to assess the association of lncRNA GHET1 expression with pathological parameters of cancer patients." (PMID 32908508, 2020). "Our results indicated that HTS in cancer patients was associated with high lncRNA GHET1 expression (pooled OR = 4.06 and 95% CI: 2.71–6.09)." (PMID 32908508, 2020). "Clinically, several studies have indicated that up-regulation of GHET1 is associated with poor prognosis and advanced clinical features in several cancers." (PMID 32280301, 2020). "The pooled results of this study indicated that high lncRNA GHET1 expression level was significantly associated with poor overall survival (OS, HR = 2.30, 95% CI: 1.75‐3.02) in human cancers." (PMID 31251476, 2019). "High lncRNA GHET1 expression is associated with worse OS and clinicopathological features compared with low lncRNA GHET1 expression in human cancers." (PMID 31227613, 2019). "Elevated lncRNA GHET1 levels in cancer tissues are significantly related to a greater risk of mortality, progression, and metastasis." (PMID 31885739, 2019). "High lncRNA GHET1 expression was associated with shorter OS than low lncRNA GHET1 expression in cancers (hazard ratio (HR) = 2.59, 95% CI = 1.93–3.47, P<0.01)." (PMID 31227613, 2019). "Higher expression of GHET1 was associated with poorer OS (HR = 2.30, 95% CI: 1.75‐3.02), and the subgroup meta‐analysis stratified by analysis type, cancer type, sample size and follow‐up time showed the similar results." (PMID 31251476, 2019). "Overall, high GHET1 expression was an unfavorable risk factor for survival outcomes in patients with cancer; thus, GHET1 might be a valuable biomarker for a variety of cancers." (PMID 32280301, 2020). "Overall, these results indicate that GHET1 might be an independent factor associated with survival of cancer patients." (PMID 32280301, 2020). "Taken together, these results revealed that a shorter OS might be associated with high lncRNA GHET1 expression in cancer patients; as a result, lncRNA GHET1 might serve as an independent factor of survival for cancer patients." (PMID 32908508, 2020). "Accordingly, a significant difference was detected in the incidence of DM between these two groups, which revealed that high lncRNA GHET1 expression could significantly predict a higher risk of incidence of DM in cancer patients." (PMID 32908508, 2020). "As far as the cancer patients were concerned, high lncRNA GHET1 expression could remarkably predict a higher risk of LTS." (PMID 32908508, 2020). "A fixed-effect model was used for mild heterogeneity across included studies (I2 = 47%, P=0.08), and results showed high lncRNA GHET1 expression was significantly associated with shorter OS than low lncRNA GHET1 expression in cancers (HR = 2.59, 95% CI = 1.93–3.47, P<0.01)." (PMID 31227613, 2019). "There is increasing evidence that high expression levels of the gastric carcinoma highly expressed transcript 1 (GHET1), a long noncoding RNA (lncRNA), are associated with cancer prognosis and may be used as a valuable biomarker for cancer patients." (PMID 31885739, 2019). "Even though inherent deficiencies exist, the present results suggest that promoted lncRNA GHET1 expression levels are associated with OS and lncRNA GHET1 may be used as a prognostic marker for cancer patients." (PMID 31885739, 2019). "For cancer patients, high lncRNA GHET1 expression could well predict the high risk of LNM." (PMID 32908508, 2020). "However, the underlying mechanisms by which lncRNA GHET1 influenced the cancer remained unknown yet." (PMID 32908508, 2020). "Previous meta-analyses have indicated that DLX6-AS1, PVT1, SNHG15 and GHET1 are related to the clinicopathological features and prognosis of various cancers." (PMID 34923990, 2021).
cancer (continued). "Several studies have demonstrated that lncRNA GHET1 promotes cell proliferation, migration and invasion in different types of cancer." (PMID 34372865, 2021). "The lncRNA gastric carcinoma high expressed transcript 1 (GHET1) has been found to be involved in the development of various types of cancer." (PMID 34372865, 2021). "As a consequence, an updated meta-analysis was performed in this study to determine the prognostic value of lncRNA GHET1 in cancer patients." (PMID 32908508, 2020). "This meta-analysis had discussed the prognostic value and clinicopathological significance of lncRNA GHET1 in cancer patients." (PMID 32908508, 2020). "The pooled results indicated that GHET1 overexpression was significantly associated with poor overall survival (OS) and disease-free survival (DFS) in cancer." (PMID 32280301, 2020). "Many studies have tried to illustrate the correlation between high GHET1 expression and cancer prognosis; however, the molecular mechanism of GHET1 remained unclear." (PMID 32280301, 2020). "In sum up, the up-regulation of lncRNA GHET1 expression was significantly associated with poor OS, poor DFS, and advanced clinicopathological characteristics in various cancers." (PMID 32280301, 2020). "There is a significant correlation between up-regulation of GHET1 and both poor prognosis and advanced clinicopathological cancer characteristics." (PMID 32280301, 2020). "The GHET1 high expression group had shorter OS than the GHET1 low expression group, confirming that over-expression of GHET1 is correlated with poor OS in various human cancers (P < 0.001)." (PMID 32280301, 2020). "Long noncoding RNA gastric cancer highly expressed transcript 1 (lncRNA GHET1) is often reported to be abnormally expressed in multiple cancers, but the situation is different in different cancers." (PMID 32908508, 2020). "According to the median GHET1 expression level, 3036 patients with 10 cancer types were classified into two groups." (PMID 32280301, 2020). "A number of studies have demonstrated the critical role of long non-coding RNA gastric cancer high expressed transcript 1 (GHET1) in many cancers." (PMID 32280301, 2020). "It is to provide preclinical data for the translational research of lncRNA GHET1 in cancer treatment." (PMID 32908508, 2020). "Meanwhile, hazard ratios (HRs) and 95% confidence intervals (CIs) were calculated to explore the relationship between lncRNA GHET1 expression and survival of cancer patients." (PMID 32908508, 2020). "Relevant research studies on lncRNA GHET1 and cancer were retrieved from three electronic literature databases of Web of Science, PubMed, and OVID." (PMID 32908508, 2020). "The pooled odds ratio (OR) and hazard ratio (HR) with 95% confidence interval (CI) were used to evaluate the role of GHET1 in cancer." (PMID 32280301, 2020). "In this meta-analysis, data regarding the association between the lncRNA GHET1 expression level and PHG were collected from the 409 cancer patients recruited in seven eligible studies." (PMID 32908508, 2020). "In order to further explore the potential prognostic value of GHET1, a series of subgroup analyses were performed based on cancer type, sample size, cut-off value, treatment, and NOS score." (PMID 32280301, 2020). "Our results indicated that OS was evidently related to lncRNA GHET1 (pooled HR = 2.28, 95% CI: 1.85–2.82) in cancer patients." (PMID 32908508, 2020). "According to previous studies, lncRNA GHET1 has been proved to be an important oncogene in various human cancers, including NSCLC, HCC, BC, ESCC, HNC, BRC, GC, and PC." (PMID 32908508, 2020). "The pooled HR indicated that GHET1 overexpression was significantly associated with poor OS and DFS in cancer." (PMID 32280301, 2020). "These evidence encouraged us to investigate the relationship between lncRNA GHET1 and cancer prognosis." (PMID 31885739, 2019).
cancer (continued). "In order to determine the prognostic significance of lncRNA GHET1 expression in human cancers, we performed this meta-analysis by integrating the current evidence." (PMID 31227613, 2019). "Firstly, this is the first study comprehensively explored the relationship between the GHET1 expression level and prognostic outcomes in human cancers based on our knowledge." (PMID 31251476, 2019). "Gastric carcinoma proliferation enhancing transcript 1 (GHET1) has been suggested to serve as a promising oncogenic lncRNA in various types of human cancer." (PMID 30948501, 2019). "Our analysis demonstrated that high expression levels of lncRNA GHET1 are an unfavorable predictor of the clinical outcomes for cancer patients." (PMID 31885739, 2019). "Subgroup analyses also indicated the obvious relationship between high lncRNA GHET1 expression and shorter OS in cancers (P<0.05)." (PMID 31227613, 2019). "Recently, increasing studies have reported that long non‐coding RNA (lncRNA) gastric carcinoma highly expressed transcript 1 (GHET1) is highly expressed in variety of cancers and relevant to poor prognosis of cancer patients." (PMID 31251476, 2019). "We, therefore, conducted this quantitative meta-analysis to investigate the prognostic value of GHET1 in various cancers." (PMID 31885739, 2019). "Five studies investigated the expression level of GHET1 and overall survival (OS) of Chinese cancer patients." (PMID 31885739, 2019). "Recently, many studies found that lncRNA GHET1 contributed to the cancer progression and had the potential ability to predict the cancer prognosis." (PMID 31227613, 2019). "GHET1 was considered as a promising oncogenic lncRNA owing to high stability, efficiency, and specificity in various types of human cancer." (PMID 30948501, 2019). "Most studies, however, that reported the prognostic value of GHET1 expression in cancer patients were limited by small sample size." (PMID 31885739, 2019). "Meta‐analysis of these studies revealed that high lncRNA GHET1 expression level was significantly relative to poor OS in human cancer (HR: 2.30, 95% CI: 1.75‐3.02)." (PMID 31251476, 2019). "The aim of this meta-analysis was to evaluate the prognostic significance of lncRNA GHET1 expression in cancers." (PMID 31227613, 2019). "LncRNA GHET1, a novel lncRNA located in an intergenic region on chromosome 7, has been found to be significantly upregulated in several types of cancers." (PMID 31885739, 2019). "There is mounting evidence to suggest that overexpression of lncRNA GHET1 is correlated with poor prognosis and progression in cancer patients." (PMID 31885739, 2019). "LncRNA GHET1 has been proved to be a key regulatory molecule in the development of many cancers." (PMID 33869194, 2021). "Collectively, lncRNA GHET1 has the ability to promote cancer development." (PMID 33869194, 2021). "Twelve studies reported OS for eight types of cancer based on GHET1 expression in 1114 patients." (PMID 32280301, 2020). "Recently, several studies have reported that lncRNA GHET1 might be related to prognosis in cancer patients." (PMID 32280301, 2020). "Further, the GHET1 high expression indicated poor prognosis in several cancer." (PMID 32280301, 2020). "Previous studies have shown that lncRNA GHET1 functioned as an oncogene in several cancers." (PMID 31682716, 2020). "Moreover, further subgroup analyses indicated that elevated GHET1 expression was significantly correlated with OS in each subgroup, regardless of the analysis model, sample size, cut-off value, treatment, cancer type, and NOS score." (PMID 32280301, 2020). "Therefore, we performed this meta-analysis of 16 eligible studies to systematically evaluate the prognostic value of GHET1 in all cancers." (PMID 32280301, 2020). "Thus, we undertook a systematic review and meta-analysis of all eligible studies to perform an evidence-based evaluation of the prognostic role of GHET1 in cancer." (PMID 32280301, 2020).
cancer (continued). "In the present study, we evaluated the prognostic value of GHET1 in cancer." (PMID 32280301, 2020). "This meta-analysis provides an evidence-based evaluation of the prognostic role of GHET1 in cancer." (PMID 32280301, 2020). "For cancer patients, high lncRNA GHET1 expression might potentially serve as an indicator of poor prognosis." (PMID 32908508, 2020). "Most existing studies suggest that GHET1 might be a potential biomarker for predicting the prognosis of human cancers." (PMID 32280301, 2020). "Therefore, a meta-analysis is necessary to clarify the value of lncRNA GHET1 as a prognostic indicator in cancer." (PMID 32908508, 2020). "GHET1 can be considered to be a promising prognostic predictor for human cancers." (PMID 32280301, 2020). "Other studies have also shown that GHET1 promotes the progression of cancer and might be a therapeutic target of cancer." (PMID 32280301, 2020). "Furthermore, high lncRNA GHET1 expression was also remarkably related to the clinicopathological parameters in cancer patients, including LTS, PHG, HTS, LNM, and DM." (PMID 32908508, 2020). "In addition, high lncRNA GHET1 expression was found to be dramatically correlated with poor OS in various cancer types." (PMID 32908508, 2020). "Our meta‐analysis suggested that lncRNA GHET1 may serve as a promising biomarker for prognosis in Asian with cancers." (PMID 31251476, 2019). "Generally, high GHET1 expression is an unfavorable biomarker for most human cancers." (PMID 30948501, 2019). "In our meta‐analysis, we found that lncRNA GHET1 might be an unfavourable prognosis factor for cancer patients." (PMID 31251476, 2019). "Thus, we aim to evaluate the relationship between lncRNA GHET1 expression and clinical outcomes in human cancers." (PMID 31251476, 2019). "Nevertheless, as aforesaid, this meta-analysis is a preliminary study to acknowledge the prognostic significance of lncRNA GHET1 expression in cancers, and more researches should be carried out to identify the optimal cut-off value of lncRNA GHET1 expression in future." (PMID 31227613, 2019). "Besides, online-cross validation also indicated that high lncRNA GHET1 expression was an unfavorable prognostic factor of cancer." (PMID 31227613, 2019). "LncRNA GHET1 expression can serve as a promising prognostic factor of cancers." (PMID 31227613, 2019). "GHET1 has been suggested to function as oncogenic role in human cancer." (PMID 30948501, 2019). "The HRs for the high lncRNA GHET1 expression group versus the low lncRNA GHET1 expression group were 2.63 (95% CI: 1.47‐4.73) in digestive system cancer and 2.22 (95% CI: 1.63‐3.02) in other cancers." (PMID 31251476, 2019). "Depletion of c-Myc reduces the ability of GHET1 to promote proliferation of cancer cells." (PMID 27129154, 2016). "GHET1 may be a potential prognostic predictor for human cancers." (PMID 32280301, 2020). "Therefore, lncRNA GHET1 could be used as a novel clinical biomarker or therapeutic target for Chinese cancer patients." (PMID 31885739, 2019). "Overall, lncRNA GHET1 expression could serve as a potential prognostic biomarker for human cancers." (PMID 31227613, 2019). "LncRNA GHET1 may serve as a promising biomarker for prognosis in Asians with cancers." (PMID 31251476, 2019). "Gastric carcinoma proliferation enhancing transcript 1 (GHET1) has been revealed to function as an oncogene in several cancers, but it has never been investigated in CC." (PMID 31682716, 2020). "It would be interesting to investigate whether the modulation of GHET1 for the interaction of VHL and HIF1α also occurs in other types of cancers." (PMID 30988076, 2019). "Nevertheless, the results were inconsistent and the systematic analysis of lncRNA GHET1 in cancers has not been inspected." (PMID 31251476, 2019). "Although accelerating evidence indicates lncRNA GHET1 may have the potential ability to predict the cancer prognosis, clear mechanism has not been obtained." (PMID 31227613, 2019).
cancer (continued). "The results indicated that, regardless of the cancer type, sample size, cut-off value, treatment, and NOS score, the up-regulation of GHET1 was significantly correlated with poor OS in all subgroup analyses." (PMID 32280301, 2020).
infection (1 paper, 2020). The state of being infected such as from the introduction of a foreign agent such as serum, vaccine, antigenic substance or organism. "Cell proliferation was clearly suppressed after 12 and 48 h of infection with GHET1 shRNAs in HL-60 and NB4 cell lines, respectively." (PMID 33123297, 2020). "The expression of GHET1 was significantly increased after infection of lentivirus carrying lncRNA GHET1 expressing vector in AML cell lines compared with infection of vector only." (PMID 33123297, 2020). "Furthermore, we infected NB4 and HL60 cell lines with lentivirus carrying lncRNA GHET1 shRNAs (3 shRNA) to knockdown the expression of GHET1, and the infection efficiency was detected by qPCR." (PMID 33123297, 2020).
GHET1 also shares sentences with these, for which no sentence is quoted: lung cancer (3 papers); esophageal squamous cell carcinoma (2); acute myeloid leukemia (1); cervical (1); Cirrhosis (1); colon adenocarcinoma (1); digestive system cancer (1); head and neck cancer (1); liver cancer (1); lung squamous cell carcinoma (1); metastatic cancer (1); pancreatic cancer (1); renal cell carcinoma (1); stomach adenocarcinoma (1).